PLCG1 (phospholipase C gamma 1)
Diseases named in the same sentence as PLCG1 in open-access papers (continued):
Sharing a sentence is not in itself a finding about the gene and the disease.
pancreatic cancer (6 papers, 2013 to 2023). "PRKCZ has been shown to correlate with metastasis potential in pancreatic cancer cells, and PLCG1 and PIK3CD have been demonstrated to be associated with invasiveness of several cancer cells." (PMID 23451142, 2013). "One of the most interesting genes identified using the approach described here is PLCG1, a hub gene that connects many pathways related to pancreatic cancer outcomes." (PMID 33431999, 2021). "Finally, to evaluate the risk and prognosis in pancreatic cancer more conveniently using pyroptosis-related genes, we constructed a prognostic model consisting of seven PRGs, including CASP4, GSDMC, NLRP1, PLCG1, IL-18, CASP1 and NLRP2." (PMID 35712482, 2022). "We predict that PLCG1 is an upstream gene of many pancreatic cancer-related pathways, and may sensitively control those pathways." (PMID 33431999, 2021). "An additional risk model PRG based on more immune-related genes (CASP4, GSDMC, IL-18, NLRP1, NLRP2, PLCG1, TIRAP, and TNF) was developed, which can be used to predict pancreatic cancer prognosis with an accuracy of medium to high." (PMID 37893166, 2023). "According to this study, PRGs risk models were defined with the combination of immune and signaling pathways genes (CASP4, GSDMC, NLRP1, PLCG1, IL-18, CASP1, and NLRP2), among which CASP4, NLRP1, PLCG1, IL-18, and CASP1 are overexpressed in pancreatic cancers." (PMID 37893166, 2023). "PLCG1 has not been reported in pancreatic cancer, and we only found that phosphorylation and translocation of PLCG1 were associated with PAAD invasion and metastasis." (PMID 35677632, 2022). "PLCG1 has also been shown to be involved in colorectal tumorigenesis by means of crosstalk with STAT329; however, its role in pancreatic cancer remains unknown, to the best of our knowledge." (PMID 33431999, 2021). "However, our careful analysis revealed an interesting phenomenon in which PLCG1 expression in pancreatic cancer was mainly found in mesenchymal cells rather than tumor cells." (PMID 35677632, 2022).
adult T cell leukemia (5 papers, 2019 to 2025). "These genes are involved in the T cell mediated pathways, the same as PLCG1 and are related to diseases like Adult T cell leukemia." (PMID 34793541, 2021). "Notably, PLCG1 is the most frequently mutated gene in adult T-cell leukemia/lymphoma (ATLL); about 36% of patients acquired mutations in PLCG1." (PMID 40796680, 2025).
depression (5 papers, 2015 to 2022). "Plcg1 was found to be positively linked to stress (4 mined sentences) and as having a regulatory role in fertility and depression, although the latter yielding medium to low confidence scores, 2 and 1, respectively." (PMID 36364936, 2022).
diabetes (5 papers, 2013 to 2023). "We identified novel targets including CLTC (clathrin heavy chain), TNS2, PLCG1 and NIFK (nucleolar protein interacting with the FHA domain of MKI67) for specific therapy of diabetes mellitus and obesity." (PMID 36837510, 2023). "Replacing WT CD40 with CD40 ΔT2,3 impaired activation of PLCγ1 in Müller cells, upregulation of P2X7 in microglia/macrophages, upregulation of a broad range of inflammatory molecules in the diabetic retina and the development of diabetic retinopathy." (PMID 35920844, 2022). "Notably, PLCG1 and DPP8 showed excellent discriminative abilities in the prediction of diabetes." (PMID 38034011, 2023).
lung carcinoma (5 papers, 2022 to 2025). "It is speculated that PLCG1 intron methylation levels may assist in the early diagnosis or prognosis evaluation of lung cancer caused by radon exposure." (PMID 40725119, 2025). "DNAm modifications of MAPK10, PLCG1, PLCβ3 and PIK3R2 genes were consistently linked between the lung and blood samples, suggesting their pivotal role in radon-induced lung cancer." (PMID 40725119, 2025). "Abnormal PLCγ1 expression has shown a positive correlation with the tumor stage and metastatic ability, supporting its potential as a target for lung cancer treatment." (PMID 40725119, 2025). "PLCG1 gene DNAm regulation within lung cancer remains unexplored." (PMID 40725119, 2025). "Besides, numerous studies have proven the involvement of PLCG1-mediated inflammatory response in the pathogenesis of osteoarthritis and lung cancer." (PMID 37008939, 2023). "The DNAm episignatures of MAPK10, PLCG1, PLCβ3 and PIK3R2 have a significant influence on radon-induced lung cancer." (PMID 40725119, 2025). "This study revealed radon exposure-induced PLCG1 hypermethylation within the intron region, correlating strongly across lung tissue and blood, and resulting in increased RNA and protein levels in the lung tissue of KRASG12D lung cancer mice." (PMID 40725119, 2025). "In addition, radon exposure promoted lung cancer development in the genetic engineering mouse model (GEMM), accompanied by decreased MAPK10 and increased PLCG1, PLCβ3, and PIK3R2 with mRNA and protein levels." (PMID 40725119, 2025).
osteoarthritis (5 papers, 2015 to 2023). A noninflammatory degenerative joint disease occurring chiefly in older persons, characterized by degeneration of the articular cartilage, hypertrophy of bone at the margins and changes in the synovial membrane. "As one of the most important members of the phospholipase family, the role of PLCγ1 in osteoarthritis, especially in chondrocytes, has become a research focus." (PMID 33326693, 2021). "This study aims to investigate whether and how PLCγ1 modulates autophagy to execute its role in osteoarthritis (OA) progression." (PMID 33372388, 2021). "Previous studies have addressed the involvement of phosphoinositide-specifc phospholipase γ1 (PLCγ1) and protein kinase B (PKB/Akt) in osteoarthritis (OA) pathogenesis, but it is not ascertained the possibility of them to be potential targets for OA therapy." (PMID 29435116, 2018).
breast tumor (4 papers, 2013 to 2019). "Studies have shown that higher levels of PLCG1 expression in breast tumours has been linked to metastasis." (PMID 29188362, 2018). "In the present study, we have shown that the prognostic role of activated PLCγ1 expression is limited to ER-positive, Luminal breast tumours." (PMID 31362705, 2019). "GRB2 interaction with LAT and LAX1 observed in breast tumor cells may be an indirect interaction through PLCG1, VAV or PIK3R1." (PMID 23826330, 2013).
colon cancer (4 papers, 2017 to 2025). "In this study, PLCγ1 conditional knockout mice and WT littermates developed colon tumors, primarily in the distal to middle segments." (PMID 29464031, 2018). "PLCγ1 conditional knockout mice and PLCγ1f/f [wild type (WT)] littermates developed colon tumors, primarily in the distal to middle segments, using the AOM/DSS protocol, consistent with the localization of human colorectal tumors, the most severe consequence of DSS-induced colitis." (PMID 29464031, 2018). "Furthermore, the effects of the IRGs on colon cancer development remain unclear, although cancer progression has been linked to CD1B, XCL1, PLCG1, NGF, and OXTR." (PMID 32508884, 2020). "Dysfunction of PLCG1 is closely associated with inflammation, immune disorders, and cancer, and in vitro testing revealed that PLCG1 mediated high glucose levels and insulin-induced cell proliferation and migration in SW480 colon cancer cells." (PMID 32508884, 2020). "In the two colon cancer cell lines, lower PLCγ1 and higher LC3B-II expression was observed in HCT116 cells and higher PLCγ1 expression and lower LC3B-II expression was observed in HCT8 cells." (PMID 29066806, 2017). "When mice were subjected to only one cycle of DSS, we noticed that WT mice only manifested colon tumors, whereas no colon tumors were detected in PLCγ1 conditional knockout mice." (PMID 29464031, 2018).
cutaneous T-cell lymphoma (4 papers, 2019 to 2023). "In a previous case–control study, missense mutations in PLCG1 were reported to participate in the pathogenesis of cutaneous T-cell lymphomas by enhancing downstream signaling towards nuclear factor of activated T-cell activation." (PMID 31681408, 2019). "The PLCG1/PKCθ axis accelerated STAT3 activation and promoted the proliferation and survival of cutaneous T-cell lymphoma cells." (PMID 36920176, 2023).
leukemia (4 papers, 2017 to 2022). A malignant (clonal) hematologic disorder, involving hematopoietic stem cells and characterized by the presence of primitive or atypical myeloid or lymphoid cells in the bone marrow and the blood. "Previous work demonstrated the dependence of BCR-FGFR1 on Grb2 for CML-like leukemia, and the importance of PLCγ1 for ZNF198-FGFR1-driven EMS like disease." (PMID 35574218, 2022). "From this work, they concluded that PLCγ1 represents a critical downstream pathway for ZNF198-FGFR1-induced disease, and that Grb2 activation was important for BCR-FGFR1 in the induction of CML-like leukemia in mice." (PMID 35574218, 2022).
lung adenocarcinoma (4 papers, 2020 to 2025). A carcinoma that arises from the lung and is characterized by the presence of malignant glandular epithelial cells. "In patients with KRAS-mutated lung adenocarcinomas, the decreased expression of PLCγ1 corresponds to increased expression of hypoxia markers and poor patient survival." (PMID 37370855, 2023). "In this study, we investigated the effect of PLCγ1 inhibition on cell proliferation and migration and its regulatory mechanism linked to autophagy in human lung adenocarcinoma A549 cells." (PMID 32210730, 2020). "However, whether and how PLCγ1 regulation in human lung adenocarcinoma is linked to autophagy remains unclear." (PMID 32210730, 2020). "Integrative and comparative genomic analysis of human lung adenocarcinoma demonstrated that PLCγ1 significantly enriched in autophagic process and regulation, which negatively regulating autophagy was enriched in higher expression of PLCγ1 (r≤-0.4, p<0.001)." (PMID 32210730, 2020). "As a result, increased PLCγ1 expression occurred frequently in human lung adenocarcinoma tissue with higher grades of T in TNM staging classification." (PMID 32210730, 2020). "The results showed that increased PLCγ1 expression occurred frequently in human lung adenocarcinoma tissue with higher grades of T in TNM staging classification." (PMID 32210730, 2020). "The majority (78.57%) of human lung adenocarcinoma specimens (T2, T3) showed a specific immune reactivity to PLCγ1 (p=0.003<0.05)." (PMID 32210730, 2020). "PLCγ1 expression in human lung adenocarcinoma was assessed by immunohistochemistry assay in a tissue microarray." (PMID 32210730, 2020). "Meanwhile, human lung adenocarcinoma A549 cells were treated with PLCγ1 inhibitor U73122 (U), following the detection of cell viability and migration." (PMID 32210730, 2020). "Therefore, AMPKα, mTOR, and ERK signals were involved in PLCγ1 inhibition-driven autophagy in human lung adenocarcinoma A549 cells." (PMID 32210730, 2020). "Here, we assessed the protein expression of PLCγ1 in human lung adenocarcinoma tissue using immunohistochemistry assay and the relationship between PLCG1 and autophagy in The Cancer Genome Atlas Network (TCGA) using Spearman correlation analysis and GSEA software." (PMID 32210730, 2020). "Collectively, either the depletion of PLCγ1 by shPLCγ1 or treatment with LiCl could suppress human lung adenocarcinoma growth in a nude mouse xenograft model of A549 cells, but a combination of shPLCγ1 with LiCl did not exhibit more efficacious than one each alone." (PMID 32210730, 2020). "However, whether and how PLCγ1 regulation is linked to autophagy has not been determined in human lung adenocarcinoma." (PMID 32210730, 2020). "Furthermore, consistent with our previous study, it was observed that PLCγ1 inhibition blocked mTOR and ULK1 phosphorylation in lung adenocarcinoma A549 cells, suggesting thereby that the suppression of PLCγ1/mTOR/ULK1 axis might contribute to PLCγ1 inhibition-driven autophagy." (PMID 32210730, 2020). "At the meantime, the data of integrative and comparative genomic analysis of human lung adenocarcinoma also showed that the negative correlation between PLCγ1 expression and autophagy regulation." (PMID 32210730, 2020). "Taken together, the data indicated that increased PLCγ1 expression occurred frequently in human lung adenocarcinoma tissue with higher grades of T in TNM staging classification and that PLCγ1 inhibition reduced cell proliferation and migration in human lung adenocarcinoma A549 cells." (PMID 32210730, 2020).
myelodysplastic syndrome (4 papers, 2020 to 2022). A clonal hematopoietic disorder characterized by dysplasia and ineffective hematopoiesis in one or more of the hematopoietic cell lines. "Other than CLL, reduced PLCG1 expression was also found to be associated with inferior survival for myelodysplastic syndromes (MDS)." (PMID 36177050, 2022). "The PLCG1 gene, which encodes the phospholipase C γ1 isoform, is located within the commonly deleted region of the long arm of chromosome 20 (del(20q)) observed in myelodysplastic syndromes (MDS)." (PMID 31755660, 2020). "The PLCG1 expression could also be a biomarker for myelodysplastic syndromes and oral squamous cell carcinoma." (PMID 35535333, 2022).
prostate carcinoma (4 papers, 2016 to 2022). A carcinoma that arises from epithelial cells of the prostate gland. "Studies have shown that PLCG1 is related to the invasive ability of various malignant tumors, such as liver, lung, and prostate cancer, but its relationship with tumor cell proliferation remains controversial." (PMID 36552744, 2022). "Targeting PLCγ1 by way of a hammerhead ribozyme to PLCγ1 reduces the invasive phenotype of prostate cancer." (PMID 26811493, 2016). "In addition, we used qRT-PCR to compare the expression of hub genes (CHMP4C, GSDMB, NOD2, PLCG1, CYCS, GPX4) between prostate cancer cell lines (LNCap, PC3, DU-145) and the normal prostate epithelial cell line (RWPE-1)." (PMID 36386841, 2022).
schizophrenia (4 papers, 2021 to 2022). A major psychotic disorder characterized by abnormalities in the perception or expression of reality. "An apparent close connection between the ketamine and BPC 157 was noted in the genes’ expression analysis in brain tissue, using Nos1, Nos2, Nos3, Plcg1, Prkcg, Ptgs2, and Ptk2 all associated with schizophrenia presentation." (PMID 35884767, 2022). "This was done with the genes’ expression analysis in brain tissue, using Nos1, Nos2, Nos3, Plcg1, Prkcg, Ptgs2, and Ptk2, all associated with schizophrenia presentation." (PMID 35884767, 2022). "The detected effect of MIA on PLCG1 is consistent with reports that PLCG1 participates in the interactome of schizophrenia." (PMID 33834688, 2021).
Sepsis (4 papers, 2021 to 2023). Sepsis is defined as life-threatening organ dysfunction caused by a dysregulated host response to infection. "The results of the ROC analysis illustrated the satisfactory diagnostic ability of CHMP7, NLRC4, and PLCG1 for sepsis." (PMID 37939116, 2023). "The qRT-PCR results showed that the expression of CHMP7 was downregulated, while NLRC4 and PLCG1 expression was upregulated in H9C2 cells stimulated with LPS to mimic in vitro sepsis model." (PMID 37939116, 2023). "The study identified seven important PRGs including CHMP7, NLRC4, PLCG1, IRF1, CASP4, NLRP1, GSDMD associated with sepsis." (PMID 37939116, 2023). "Our results showed the expression of AIM2, CASP4, NLRC4, and PYCARD was higher and the expression of PVJK and PLCG1 was lower in both sepsis and septic shock patients than in healthy controls." (PMID 36250055, 2022). "A previous study found that GSDMD N-terminal-mediated pyroptosis is dependent on the PLCG1 gene in sepsis." (PMID 35741587, 2022). "Compared to that of healthy individuals, the expression level of AIM2, CASP4, NLRC4, and PYCARD was significantly upregulated, while the expression level of PVJK and PLCG1 was significantly downregulated in both sepsis and septic shock patients." (PMID 36250055, 2022). "In addition, the expression of CHMP7, NLRC4, and PLCG1 in an in vitro sepsis model was further validated." (PMID 37939116, 2023). "GSEA showed that PLCG1 was related to the T-cell receptor signaling pathway with NES of −1.55 in the sepsis group, indicating that this impaired pathway may mediate the progress of sepsis." (PMID 36250055, 2022). "In addition, an external GSE185263 dataset was utilized to validate the two genes, and the results showed that the expression of PLCG1 was greatly lower in the sepsis group than in the healthy group, and the expression of CASP4 was higher." (PMID 36250055, 2022). "Interestingly, the expression level of PLCG1 was continuously significantly decreased during sepsis development, while the expression level of NLRC4 was gradually significantly elevated." (PMID 36250055, 2022). "In addition, we found the upregulation of NLRC4 and the downregulation of PLCG1 participated during sepsis progression." (PMID 36250055, 2022). "The expression level of PLCG1 was continuously significantly decreased, while the expression level of NLRC4 was elevated from control to sepsis and then to septic shock." (PMID 36250055, 2022). "Specifically, PLCG1, one of the hub genes, was related to the T-cell receptor signaling pathway, and the normalized enrichment score (NES) was −1.55 in the sepsis group, indicating that this pathway was impaired in sepsis patients." (PMID 36250055, 2022). "GPX4 was found to negatively regulate Gasdermin D-mediated pyroptosis in lethal polymicrobial sepsis by reducing lipid peroxidation; in contrast, conditional GPX4 knockdown in myeloid cells triggers macrophage pyroptosis with caspase-1/caspase-11-GSDMD-phospholipase C gamma 1 axis." (PMID 34899864, 2021). "Therefore, PLCG1 and NLRC4 may mediate the development of sepsis." (PMID 36250055, 2022).
angioimmunoblastic T-cell lymphoma (3 papers, 2019 to 2021). A mature T-cell non-Hodgkin lymphoma, characterized by systemic disease and a polymorphous infiltrate involving lymph nodes and extranodal sites. "Similarly, PLCG1 G797E corresponds to human G869E, an established gain-of-function mutant in angioimmunoblastic T cell lymphoma." (PMID 32210430, 2020).
COVID-19 (3 papers, 2022 to 2023). A disease caused by infection with severe acute respiratory syndrome coronavirus 2. "The area under the curve (AUC) values for 6 shared hub genes (CDC6, PLCG1, KIF15, LCK, CDC25C, and RASGRP1) in the SLE dataset to discriminate between patients and healthy controls were greater than 0.61, while those for the COVID-19 dataset were greater than 0.91." (PMID 37426642, 2023).